ARL14 (ARF like GTPase 14)
Description:
GTPase that recruits MYO1E to MHC class II-containing vesicles via the effector protein ARL14EP and hence controls the movement of these vesicles along the actin cytoskeleton in dendritic cells.
Synonyms: ARF7; FLJ22595
Tractability: Antibody: its Gene Ontology location is reachable by antibodies, with medium confidence.
Gene: Protein-coding gene on chromosome 3 (160,677,160 to 160,678,448, forward strand). Ensembl gene ENSG00000179674.
Subcellular location: Cytoplasmic vesicle
Gene Ontology:
Molecular function: protein binding; GTP binding; GTPase activity
Biological process: intracellular protein transport; establishment of cell polarity
Cellular component: plasma membrane; cytoplasmic vesicle
Genetic constraint (gnomAD): Loss-of-function variants: 8 observed, 8.25 expected, observed/expected ratio (o/e) 0.97, 90% interval 0.57 to 1.68. That is too few expected variants to judge how well the gene tolerates losing a copy. Missense variants: 264 observed, 234.96 expected, observed/expected ratio (o/e) 1.12, 90% interval 1.01 to 1.24. Synonymous variants: 99 observed, 88.86 expected, observed/expected ratio (o/e) 1.11, 90% interval 0.95 to 1.32.
Homologues: Orthologues: chimpanzee ARL14 (99% identical), dog ARL14 (86% identical), rabbit ARL14 (85% identical), pig ARL14 (85% identical), guinea pig ARL14 (84% identical), macaque ARL14 (78% identical), rat Arl14 (77% identical), mouse Arl14 (75% identical), tropical clawed frog arl14 (64% identical). Paralogues in human: ARL11 (42% identical), ARF3 (41% identical), ARF5 (41% identical), ARF1 (41% identical), ARF4 (40% identical), ARL4D (40% identical), ARF6 (39% identical), ARL4C (39% identical), TRIM23 (39% identical), ARL1 (38% identical), ARL3 (38% identical), ARL2 (35% identical), and 18 more.
Diseases named in the same sentence as ARL14 in open-access papers:
ARL14 is named in the same sentence as 24 diseases in open-access papers, as found by Europe PMC text mining. Sharing a sentence is not in itself a finding about the gene and the disease. The quoted sentences say what the papers report.
malaria (4 papers, 2018 to 2025). Malaria is a serious and sometimes fatal disease caused by a parasite that commonly infects a certain type of mosquito which feeds on humans. "Beyond lung cancer, genetic variation at the ARL14 locus has been linked to susceptibility or resistance to malaria, as demonstrated by the presence of single nucleotide polymorphisms in the ARL14 gene." (PMID 41446580, 2025). "We identified an ARL14 cis-regulatory region containing functional single-nucleotide polymorphisms (SNPs) associated with severe malaria and provided evidence of allele-specific promoter activity." (PMID 38531688, 2024). "We suggest that these SNPs regulate ARL14 expression in immune cells and the presentation of antigens to T lymphocytes, thus influencing severe malaria development." (PMID 38531688, 2024). "Hence, these SNPs could be involved in the development of severe malaria by regulating ARL14 expression and consequently T-lymphocyte activation." (PMID 38531688, 2024). "Two polymorphisms on the genes ARL14 and LOC727982, reported previously as associated with protection in severe malaria (neither of which are related to red cells), showed decreased effect sizes and –log10 p-values and are thus potentially spurious hits." (PMID 34225842, 2021). "Likewise, although significant associations were seen between severe malaria and polymorphisms in seven additional genes (IL10, LPHN2 [ADGRL2], LOC727982, ARL14, RPS6KL1, CAND1, and GNAS), without further data their potential for translation remains elusive." (PMID 30033078, 2018).
lung carcinoma (3 papers, 2019 to 2025). "ARL14 is located on human chromosome 13q14.2, a region closely related to several cancers including lung cancer and involved in multidrug resistance in cancer treatment." (PMID 31750299, 2019). "These genes include GRIA3, TAF7L, ARL14, PCDHGA9, MDGA1, ZFPM2, OSR2, TMC8/TMC6, HCN2, and CDK5R2, which are likely to be relevant in human lung cancer and are also epigenetically deregulated upon exposure to ECS in our animal study." (PMID 39273313, 2024). "ARL14, normally expressed in the gastrointestinal tract, is ectopically upregulated in NSCLC and correlated with poor prognosis, raising questions about transcriptional regulation and selective advantages in lung cancer cells." (PMID 41446580, 2025). "Analyses of “The Cancer Genome Atlas” (TCGA) lung cancer cohorts revealed that ARL14 expression is upregulated in non-small cell lung cancer (NSCLC), including lung squamous cell carcinoma and lung adenocarcinoma (LUAD) with elevated ARL14 expression correlated with poor patient prognosis." (PMID 41446580, 2025).
lung adenocarcinoma (2 papers, 2019 to 2025). A carcinoma that arises from the lung and is characterized by the presence of malignant glandular epithelial cells. "This study was conducted to determine the function and possible underlying mechanisms of ARL14 in lung adenocarcinoma tumorigenesis." (PMID 31750299, 2019). "We found that ARL14 had significantly different levels between lung adenocarcinoma samples and matched normal control tissues as well between lung adenocarcinoma cells and normal lung cells, and ARL14 level is associated with the prognosis of lung adenocarcinoma." (PMID 31750299, 2019). "Our measurement further confirmed that the expression levels of ARL14 in lung adenocarcinoma cells (A549 and PC9) were higher than that in normal lung cells (BEAS-2B and MRC-5), which is consistent with the results obtained from TCGA cohort." (PMID 31750299, 2019). "In this study, ARF-like GTPase 14 (ARL14) was screened as an important prognostic factor of lung adenocarcinoma from The Cancer Genome Atlas (TCGA) database and validated by our in vitro experiments." (PMID 31750299, 2019). "Our results revealed the contribution of ARL14 in lung adenocarcinoma tumorigenesis and suggested that ARL14 might have potential implication as a diagnostic biomarker and therapeutic target for lung adenocarcinoma." (PMID 31750299, 2019). "We wonder whether ERK and p38 signaling pathways are regulated by ARL14 in lung adenocarcinoma cells." (PMID 31750299, 2019). "Therefore, ARL14 may be applied as an ideal prognostic biomarker and therapeutic target of lung adenocarcinoma." (PMID 31750299, 2019). "Therefore, ARL14 might become a candidate prognostic factor of lung adenocarcinoma development and is worthy of further investigation of its function." (PMID 31750299, 2019). "Moreover, silencing ARL14 inhibited the proliferation, migration and invasion of lung adenocarcinoma cells but it had no influence on the proliferation of normal lung cells." (PMID 31750299, 2019).
bladder cancer (1 paper, 2022). "The expression of ARL14 corresponds positively to prognosis in bladder cancer." (PMID 35333898, 2022).
colon cancer (1 paper, 2023). "Congruent with these observations, H3K27me3 was enriched at the promoter and coding regions of ARL14 and HOXA2 genes in SW620 colon cancer cells but largely disappeared following B32B3 and Taz treatment." (PMID 37069142, 2023).
endometrial cancer (1 paper, 2022). Primary or metastatic malignant neoplasm involving the endometrium (mucous membrane that lines the endometrial cavity). "In the case of the ADP-ribosylation factor (ARF)/ARF-like protein (ARL) family, it was observed that a high expression of ARL4D, ARL1, ARF1, and SAR1B in endometrial cancer is associated with better prognosis, while a high expression of ARL4C, ARL2, ARL10, ARL16, and ARL14 promotes worse survival." (PMID 35163161, 2022).
gastric cancer (1 paper, 2023). A primary or metastatic malignant neoplasm involving the stomach. "ARF3, a homolog of ARL14, is said to express itself insufficiently in gastric cancer and may function as a possible biomarker for the prognosis of gastric cancer." (PMID 36874133, 2023).
idiopathic inflammatory myopathies (1 paper, 2024). "ARL14 genetic variation was previously found to be associated with immune disorders such as systemic sclerosis, systemic lupus erythematosus, rheumatoid arthritis, and idiopathic inflammatory myopathies." (PMID 38531688, 2024).
cancer (6 papers, 2016 to 2023). A tumor composed of atypical neoplastic, often pleomorphic cells that invade other tissues. "Seldom study has evaluated the transcriptional regulation of ARL14 in human cancers." (PMID 31750299, 2019). "Besides cancer-related genes, three genes ARL14, CELSR3, and WFDC3 are also observed in our list." (PMID 27610367, 2016). "However, the function of ARL14 in the formation and progression of human cancer is unknown." (PMID 31750299, 2019). "ARL14 could promote LUAD cell proliferation, and knockdown of ARL14 induced a dormant state in cancer cells." (PMID 36941988, 2023). "However, information regarding the role of ARL14 in cancer is lacking." (PMID 31516386, 2019).
tumor (4 papers, 2019 to 2025). "Higher ARL14 expression was linked to residual tumor in lung adenocarcinoma (P = 0.017), although it was related to age (P = 0.003) and N stage (P = 0.009) in lung squamous cell carcinoma." (PMID 36874133, 2023). "The ARL14 gene encodes a protein member of the Ras super-family composed of 196 amino acids which is involved in apoptotic signaling and several regulatory pathways, indicating its usefulness as a marker for predicting tumor progression and prognosis." (PMID 31750299, 2019). "In training set (TCGA), ZDHHC11B and HLF were significantly downregulated in tumor samples, whereas ARL14 was significantly upregulated (P < 0.05)." (PMID 39901294, 2025). "Among them, ARL14 was significantly upregulated in tumor samples, while ZDHHC11B and HLF were downregulated." (PMID 39901294, 2025). "The expression of ARL14 in tumor tissues and standard samples was compared using immunohistochemistry (IHC)." (PMID 36874133, 2023). "So far, work on mammalian PSDs has revealed functions for C-terminal domains in regulating ARF6, ARF1 or ARL14 during actin cytoskeletal reorganisation and membrane ruffling, tumour formation, axon regeneration and immune regulation." (PMID 31718774, 2019). "As expected, ARL14 was significantly up-regulated in tumor samples, while ZDHHC11B and HLF were clearly down-regulated in tumor." (PMID 39901294, 2025).
ARL14 also shares sentences with these, for which no sentence is quoted: infection (3 papers); adenocarcinoma (1); bacterial infections (1); colorectal cancer (1); cystitis (1); immune disorders (1); Insulin resistance (1); lung squamous cell carcinoma (1); lymph node metastases (1); metabolic disorders (1); non-small cell lung carcinoma (1); rheumatoid arthritis (1); systemic lupus erythematosus (1); systemic sclerosis (1).